BCAT2 (branched chain amino acid transaminase 2)
Diseases named in the same sentence as BCAT2 in open-access papers (continued):
Sharing a sentence is not in itself a finding about the gene and the disease.
cancer (continued). "Enzymes that catalyze the first step of BCAA degradation, branched-chain aminotransferase 1 (BCAT1) and branched-chain aminotransferase 2 (BCAT2), are commonly upregulated in cancer cells." (PMID 35155562, 2021). "Compared to the parental cancer cells, BCAT2-knockdown cells showed smaller mitochondria morphology with more condensed mitochondrial membrane density, and reduced mitochondria crista, which are typical morphological features of ferroptosis." (PMID 33097833, 2021). "SREBP1 knockout HepG2 cancer cells using CRISPR-Cas9 technology displayed the down-expression of BCAT2." (PMID 33097833, 2021). "The Cancer Genome Atlas (TCGA) data analysis showed that BCAT2 expression correlated with cancer grade and the expression of ferroptosis markers (GPX4 and NCOA4) in HCC." (PMID 33097833, 2021). "BCAT2 gene silencing experiments in cancer and normal cells were performed to assess the impact of branched chain amino acid degradation on cell proliferation." (PMID 28798381, 2017). "The dependency on the two BCAT isoenzymes, BCAT1 and BCAT2, differs across cancers." (PMID 40438606, 2025). "Research investigating the role of BCAT2 in cancer has unveiled a more intricate mechanism." (PMID 40274762, 2025). "BCAT2 can also be used to predict cancer cell responsiveness to ferroptosis-inducing therapies and be used as a sensitive biomarker to evaluate drug response in preclinical cancer models." (PMID 38028625, 2023). "Furthermore, T‐cell‐mediated cancer cell killing assay was used to explore the cytotoxicity variation of T cells after direct contact with tumor cells expressed different level of BCAT2." (PMID 36642843, 2023). "Therefore, highly specific BCAT2 inhibitors can provide an effective treatment for a subset of cancer patients." (PMID 38028625, 2023). "Therefore, pattern of majority expression on malignant cells inferred that BCAT2 acts an immunoregulator part in TME mainly by means of varying characteristic of cancer cell." (PMID 36642843, 2023). "We suggest that the protein or mRNA level of BCAT2 may be used to predict the responsiveness of cancer cells to future ferroptosis-inducing therapies." (PMID 33097833, 2021). "Due to the critical role of glutamine metabolism in ferroptosis, treated BCAT2 overexpression cancer cells with 6-diazo-5-oxo-L-norleucine (DON, glutaminase inhibitor) could abolish the protective effect of BCAT2 in ferroptotic cancer cell death." (PMID 33097833, 2021). "We also propose that highly specific BCAT2 inhibitors could provide an effective therapy for a meaningful fraction of cancer patients." (PMID 33097833, 2021). "This general observation at the gene expression level was confirmed at the protein level for the enzyme BCAT2 in the cancer cell line MCF-7, the primary cell culture BCC isolated from tumor (which showed high BCAT2 levels), ASM and MCF-10A cells, in which it was lowly expressed." (PMID 28798381, 2017). "Higher abundance of BCAT2 in cancer cells was observed as compared with healthy cells." (PMID 28798381, 2017). "Our experiments on BCAT2 demonstrate how the described transcriptional hallmarks could potentially be exploited as therapeutic windows to target selectively cancer cells while keeping unaffected healthy dividing cells." (PMID 28798381, 2017). "Thus, BCAT2 inhibitors could potentially synergize with treatments that induce oxidative stress or ferroptosis in cancer cells." (PMID 41502503, 2025). "Similarly, the regulation of BCAT2 expression in cancer has been reported in the literature." (PMID 40438606, 2025). "Besides, BCAT2 widely expresses in various cancer cell lines." (PMID 36642843, 2023). "In conclusion, during the growth and proliferation of pancreatic ductal cancer cells, BCAT2 was involved in different pro-proliferative pathways, and inhibition of malignant tumor proliferation by gene knockout of BCAT2 may confer this strategy for targeted therapy of pancreatic ductal cancer." (PMID 36119495, 2022).
cancer (continued). "Finally, our results demonstrate the synergistic effect of sorafenib and sulfasalazine in downregulating BCAT2 expression and dictating ferroptotic death, where BCAT2 can also be used to predict the responsiveness of cancer cells to ferroptosis-inducing therapies." (PMID 33097833, 2021). "A framework is presented to categorize the differential reliance of various cancers on key catabolic enzymes-BCAT1, BCAT2 and BCKDK-underscoring their therapeutic vulnerability." (PMID 41769003, 2026). "Therefore, any cancer therapy targeting BCAT2 might require short-term dosing or targeted delivery." (PMID 41502503, 2025). "Another recent study reported that branched-chain amino acid aminotransferase 2 (BCAT2), which converts BCAA to branched-chain keto acid (BCKA) in the BCAA catabolic pathway, can suppress ferroptosis in cancer cells." (PMID 38016961, 2023). "BCAT2 is expressed widely in human tissues, while BCAT1 is highest in brain, kidney, and upregulated with cancer progression." (PMID 37918802, 2023). "We next further explore the relationship between SREBP1 and BCAT2 in both SREBP1 knockout and knockdown HepG2 cancer cells." (PMID 33097833, 2021). "Based on the available studies, the enzymes involved in the catabolism of BCAAs, such as BCAT1, BCAT2, and BCKDK, could be potential therapeutic targets for cancer treatment." (PMID 37637065, 2023). "Cytosolic branched-chain aminotransferase 1 (BCAT1) and mitochondrial branched-chain aminotransferase 2 (BCAT2), metabolic enzymes of BCAA, appear to vary between cancer types, but BCAT1′d expression is correlated with increased aggression of growth and progression." (PMID 35054779, 2022). "Moreover, the expression level of BCAT2 was further reduced in the presence of erastin, sorafenib, or sulfasalazine in the SREBP1 knockout HepG2 cancer cells." (PMID 33097833, 2021). "There was no change in viability of all tested cancer and healthy BCAT2 siRNA-treated cells, as determined by Annexin V-PE/7-AAD staining." (PMID 28798381, 2017). "Considering the undisputed but not yet fully understood role of BCAT2 in immunological processes in cancer and TB infection, one may not exclude its involvement during SRLV infection and its possible role as a susceptibility marker." (PMID 39452702, 2024). "However, some studies reported that BCAT1 and BCAT2 are not involved in human cancers such as PDAC because these enzymes can not induce PDAC tumor formation." (PMID 37637065, 2023). "Furthermore, immunostaining showed that both BCAT1 and BCAT2 were highly expressed in cancer cells when comparing noncancerous cholangiocytes (FS1 is a representative case)." (PMID 37076565, 2023). "Additionally, the cells were supplemented with branched chain keto acids which failed to recover cell growth in the presence of gabapentin, demonstrating that inhibition of cancer cell growth was not due to inhibition of BCAT2." (PMID 34292410, 2021). "For example, malignancies that lack BCAT activity and have little dependency on BCAAs or those that rely on BCAT2 activity rather than BCAT1." (PMID 34292410, 2021).
tumor (31 papers, 2017 to 2026). "Among the critical enzymes involved in the BCAA metabolic pathway, only BCAT2 demonstrated significant expression in PCa and was closely associated with tumor progression and patient prognosis." (PMID 40274762, 2025). "Consistently with its oncogenic role and regulation mechanism on chemokines in vitro, BCAT2 deficiency inhibited tumor growth and prolonged survival time in vivo, by upregulating CD8+T related chemokines." (PMID 36642843, 2023). "More importantly, cytotoxicity indicators (GZMB, IFN‐γ, TNF‐α, and Perforin) of CTLs were also reinforced in murine tumor with BCAT2 loss and combination treatment compared to corresponding control." (PMID 36642843, 2023). "In pancreatic ductal adenocarcinoma (PDAC), the concentrations of BCAA levels are significantly elevated, which is associated with tumor growth and development because BCAT2 is upregulated in PDAC, and the inhibition of this enzyme is associated with suppressing PDAC progression." (PMID 37637065, 2023). "The results indicated a significant reduction in tumor volume and quality following BCAT2 KD, whereas BCAT2 overexpression resulted in a marked increase in these parameters." (PMID 40274762, 2025). "Knockdown (KD) of BCAT2 has been shown to significantly impede tumor progression, while a diet low in BCAAs was reported to inhibit the development of PDAC in murine models." (PMID 40274762, 2025). "The BCAT2 inhibitor significantly slowed tumor growth and, intriguingly, induced markers of ferroptotic cell death in the tumors." (PMID 41502503, 2025). "Upregulation of BCAT2 appears to play a carcinogenic role in PCa by promoting tumor cell proliferation, invasion, and migration." (PMID 40274762, 2025). "Intriguingly, our proteomic data showed that in contrast to normal liver, DEN and CCl4-induced HCC mice tumor tissues expressing BCKDH complex were down-regulated while expressing BCAT2 was up-regulated." (PMID 38580754, 2024). "Together, we demonstrated that on the human tissue level, BCAT2 also mainly expressed on tumor cells and BCAT2+ tumor cell has exclusive spatial relationship with CD8+T cell." (PMID 36642843, 2023). "By quantifying the expression of BCAT1/2 in each specimen, we confirmed that the expression of BCAT1 and BCAT2 was significantly increased in tumours." (PMID 37076565, 2023). "According to panoramic analysis of tissue microarray (TMA), we found a mutual exclusive relationship between CTLs and BCAT2+tumor cells in spatial distribution." (PMID 36642843, 2023). "More importantly, in multidimensional distance gradient analysis (0–25, 25–50, 50–100, and 100–150 μm) around BCAT2+ tumor cells, counts of CD8+T cells were gradually increasing from near to far." (PMID 36642843, 2023). "Multicolor IF staining of BCAT2+ tumor cells (BCAT2+CK19+) and BCAT2+CD8+T cells were conducted in TMA and semiautomatic analyzed using TissueFAXS panoramic quantification platform." (PMID 36642843, 2023). "As anticipated, overexpression of BCAT2 significantly enhanced proliferation, migration and invasion ability of tumor cells and knockdown of BCAT2 markedly suppressed these behaviors." (PMID 36642843, 2023). "Immunoassays reveal that secretion of CD8+T‐cell‐related chemokines keeps a robust negative correlation with BCAT2, generating a decreasing tendency of CD8+T cells around BCAT2+ tumor cells from far to near." (PMID 36642843, 2023). "The expression of genes involved in the degradation of BCAA decreased but BCAT1 and BCAT2 were upregulated in the tumour tissues." (PMID 37076565, 2023). "Overexpression of BCAT2 on tumor cells directly suppressed cytotoxic function of T cells and knock down of BCAT2 on tumor cells significantly reversed the tendency." (PMID 36642843, 2023). "In line with this expression of related catabolic enzymes such as BCAT2 are increased in tumor tissues, although other enzymes are undetectable." (PMID 33924061, 2021).
tumor (continued). "Some research has demonstrated that BCAT2 expressed aberrantly in multiple kinds of neoplasms." (PMID 41457818, 2026). "For example, encapsulating a BCAT2 inhibitor in a nanoparticle to concentrate its effect in the tumor could minimize systemic exposure and toxicity." (PMID 41502503, 2025). "For example, BCAAs metabolic reprogramming was exhibited in tumor tissues of both S-III and DEN and CCl4-induced HCC mouse models, but upregulation of BCAT1 and BCAT2 was detected in tumor tissues of S-III, whereas only upregulation of BCAT2 was detected in DEN and CCl4-induced HCC mouse model." (PMID 38580754, 2024). "According to expression pattern of BCAT2 in scRNA level, specifically expressed in tumor cells rather than in immune cells and endothelial cells, we can preliminarily infer that BCAT2 loss or inhibitor of BCAT2 less likely results in terrible adverse effects." (PMID 36642843, 2023). "The expression of BCAT1 and BCAT2 was upregulated in tumours in the three cohorts." (PMID 37076565, 2023). "In the aspect of immunotherapy efficacy, although anti‐PD‐1 monotherapy could partly decrease tumor burden, cotreatment of BCAT2 KD and anti‐PD‐1 monoclonal antibody (mab) indicated a better tumor suppression effect and gained more survival benefit." (PMID 36642843, 2023). "Notably, the expression of BCAT1 and BCAT2 was ubiquitously upregulated in tumour samples relative to that in the respective normal tissues in our multi-sampling cohort." (PMID 37076565, 2023). "Lower expression of BCAT2 might be an antagonistic signal for tumor cells that use BCAAs as nitrogen source." (PMID 34646394, 2021). "To avoid the off-target action of erastin, we also performed the rescue experiments using N-acetyl-cysteine (NAC, an antioxidant ferroptosis inhibitor) and found that the protective role of BCAT2 on erastin-induced tumor growth inhibition was significantly abolished in the presence of NAC." (PMID 33097833, 2021). "In addition, we found Ki67 staining to be more intense in the tumor xenograft cells re-expressing BCAT2 K44R than it was in the Flag-BCAT2 WT cells." (PMID 32467562, 2020). "Additionally, treatment with BCAT2-IN-2 substantially decreased both tumor volume and mass." (PMID 40274762, 2025). "However, BCAT1 and BCAT2 were upregulated in tumours in our cohort and GSE26566." (PMID 37076565, 2023). "Furthermore, alongside on tumor cells, a small proportion of BCAT2 also expressed on CD8+T cells." (PMID 36642843, 2023). "Similarly, PDAC and non–small cell lung carcinoma (NSCLC) obtain BCAAs as a nitrogen source, whereas deletion of BCAT1 and BCAT2 could prevent NSCLC tumor formation in vivo but has limited effect on PDAC tumor growth." (PMID 33882453, 2021). "Thus, activity of BCAT2 may potentially fuel tumor growth through the further degradation of BCKAs and compromise normal brain tissue to favor tumor expansion." (PMID 28681360, 2017). "In vivo experiments, a xenograft MM mouse model was established using transfected knockout or overexpressing CDKN1A and BCAT2 cell lines, for analyzing the effects of CDKN1A or BCAT2 genes on tumor growth and MM cell autophagy." (PMID 41457818, 2026). "Compared with normal mouse liver tissues, the expression of BCAT2 was higher, while the expressions of BCKDHA and DBT were lower in the tumor tissues of DEN and CCl4-induced HCC mouse models." (PMID 38580754, 2024). "However, interaction of BCAT2+ tumor cell and CD8+T cell is still unknown in human tissue level." (PMID 36642843, 2023). "However, Mayers and colleagues found decreased SLC7A5, BCAT1, BCAT2 and BCKDH expression in PDAC tissue, and loss of BCAT2 does not affect PDAC tumor formation." (PMID 33882453, 2021). "BCAT2, which regulates BCAA catabolism, was upregulated in treatment-sensitive samples, and its role in modulating the tumor microenvironment suggests it could impact therapeutic sensitivity." (PMID 40083932, 2025).
tumor (continued). "Inhibition of BCAT2 can transform a noninflamed tumor microenvironment (TME) to an inflamed TME by regulating secretion levels of CD8+T‐cell‐related chemokines." (PMID 36642843, 2023). "With similar population of leukocytes and T cells in tumor, a higher proportion of CD8+T cells was shown in BCAT2 deficiency group than in negative control group." (PMID 36642843, 2023). "The loss of enzymes responsible for BCAAs utilization, Bcat1 and Bcat2, impairs NSCLC tumor formation, although these enzymes are not essential for PDAC tumor formation." (PMID 40438606, 2025). "The possible reason for this is the extremely low expression of BCAT1 in tumor tissues of DEN and CCl4-induced HCC mouse models, suggesting that DEN and CCl4-induced HCC mouse models are more suitable for the study of BCAT2 rather than BCAT1 in HCC." (PMID 38580754, 2024). "The genes encoding proteins involved in production of the branched-chain amino acids leucine, isoleucine and valine (BCAT2, BCAT1) were also increased in tumor vs. non-transformed tissue." (PMID 36831650, 2023). "We found that ~40 enzymes involved in BCAA catabolism were suppressed in tumours, with the exception of BCAT1 and BCAT2 that were upregulated in the transcriptome but not detected in the proteome." (PMID 37076565, 2023).
BCAT2 also shares sentences with these, for which no sentence is quoted: chronic myeloid leukaemia (2 papers); heart failure (2); lymphoma (2); metabolic disease (2); neurological disorders (2); adenocarcinoma (1); Alzheimer disease (1); breast tumor (1); chronic renal insufficiency (1); citrullinemia type I (1); Cognitive impairment (1); cystinuria (1); developmental delay (1); Failure to thrive (1); gallbladder cancer (1); Glucose intolerance (1); Hepatic steatosis (1); homocystinuria (1); hypermethioninemia (1); Hypervalinemia (1); ischemia (1); lipid metabolism disorders (1); lung adenocarcinoma (1); myeloid leukaemia (1); myocardial infarction (1); optic atrophy (1); prostatic intraepithelial neoplasia (1); retinal degeneration (1); sarcoma (1); Skeletal muscle atrophy (1).
A further 4 diseases each share a sentence with BCAT2 in 1 paper.